TF (transferrin)
Diseases named in the same sentence as TF in open-access papers (continued):
Sharing a sentence is not in itself a finding about the gene and the disease.
synucleinopathies (1 paper, 2022). "In this study, we assessed serum transferrin sialylation isoform profiles in de novo treatment‐naive PD and prodromal synucleinopathy (iRBD) patients and in controls and their relations to clinical and imaging parameters." (PMID 35128728, 2022). "Future studies in prodromal synucleinopathies with longer follow‐up should include serial measurement of sialylated isoforms of transferrin and other proteins to better understand the time frame, extent, and mechanisms of abnormal protein sialylation in PD and other synucleinopathies." (PMID 35128728, 2022). "However, it is not known whether altered transferrin sialylation is an early marker of prodromal synucleinopathy or a late marker of fully developed disorder." (PMID 35128728, 2022).
temporal lobe epilepsy (1 paper, 2021). A localization-related (focal) form of epilepsy characterized by recurrent seizures that arise from foci within the temporal lobe, most commonly from its mesial aspect. "Similar to this study, increased expression of MOG, PLP1, ABCA2, FA2H, TF, ASPA was demonstrated in high-spiking regions of cortical areas of temporal lobe epilepsy patients." (PMID 34301297, 2021).
teratoma (1 paper, 2020). A non-seminomatous germ cell tumor characterized by the presence of various tissues which correspond to the different germinal layers (endoderm, mesoderm, and ectoderm). "While growth factor-based protocols might be more vulnerable to this complication, teratoma formation after transplantation has also been observed in the context of TF overexpression paradigms." (PMID 32508594, 2020).
Testicular atrophy (1 paper, 2006). Wasting (atrophy) of the testicle (the male gonad) manifested by a decrease in size and potentially by a loss of fertility. "Compared to controls, AT rats displayed a reduction in testicular size and weight, with histological testicular atrophy, decreased cellular proliferation and transferrin expression, and all of these alterations were slightly improved by IGF-I at low doses." (PMID 16504030, 2006). "Transferrin expression was decreased in AT rats (1.83 ± 0.43 points, p < 0.001 vs groups CO and AT+IGF) as compared with controls (3.85 ± 0.15 points) and to rats with testicular atrophy receiving IGF-I (2.60 ± 0.30 points, p < 0.001 vs groups CO and AT+IGF)." (PMID 16504030, 2006).
testicular cancer (1 paper, 2024). A primary or metastatic malignant neoplasm that affects the testis. "The altered expression of iron metabolism-related proteins in almost all of the canine testicular neoplasia suggests their significance as potential therapeutic targets; therefore, the delivery of transferrin-chemotherapic conjugates via TfR1 should be considered in canine testicular cancers." (PMID 39272404, 2024).
tetanus (1 paper, 2013). A serious infectious disorder that follows wound contamination by the Gram-positive bacterium Clostridium tetani. "Tetanus Toxoid (TT) responses were tested in 2 individuals and TT specific cells (2.82% CD25+134+ of CD4+ T cells) had a distinctly different TF expression pattern." (PMID 24124462, 2013).
thrombotic microangiopathy (1 paper, 2022). The syndromes of microangiopathic hemolytic anemia, thrombocytopenia, and variable signs of organ impairment, due to platelet aggregation in the microcirculation. "Alongside complement’s action, the neutrophils, which produce TF and release neutrophil extracellular traps (NETs) that carry active TF, are also a part of the innate immune response, which results in a hyperinflammatory reaction and thrombotic microangiopathy." (PMID 36295093, 2022).
thyroid tumor (1 paper, 2011). A benign or malignant neoplasm affecting the thyroid gland. "Additionally, the present observations support the rationale for the use of radiolabeled transferrin/transferrin analogs and/or anti-TfR1/CD71 antibodies for diagnostic and/or radiotherapeutic purposes in TfR1/CD71-expressing thyroid tumors." (PMID 22654559, 2011).
tick-borne infections (1 paper, 2024). "Moreover, among those with negative serology for tick-borne infections, there was an improvement in low CD3% and CD3+ counts, which was more pronounced in patients with deficient transferrin amounts." (PMID 38399784, 2024).
tubulointerstitial nephritis (1 paper, 2022). "Because of limited data availability, it is currently unknown whether increased urinary transferrin concentration reflects primarily tubulointerstitial nephritis or primary glomerular disease, taking into account that tubulointerstitial nephritis is the most common lesion in CKD cats." (PMID 35218249, 2022).
uremia (1 paper, 2014). A clinical syndrome associated with the retention of renal waste products or uremic toxins in the blood. "Similarly, non-enzymatic glycation of transferrin, a process that may occur in uremia and diabetic subjects does not appear to interfere with HPLC-based CDT measurement." (PMID 24885510, 2014).
urinary tract infection (1 paper, 2021). "Plasma biomarkers included glycated hemoglobin, creatinine, cholesterol and triglycerides, as well as urine albumin, transferrin and evidence of urinary tract infection." (PMID 34743740, 2021).
vaginal infection (1 paper, 2024). "In a mouse vaginal infection model, the trivalent vaccine was modestly effective (9.2% decrease in mean area under curve compared to the pCold-TF control mice), which was somewhat better than the protection seen with the monovalent vaccines." (PMID 39660148, 2024).
vitamin A deficiency (1 paper, 2022). Deficiency of vitamin A due to malnutrition, malabsorption, or dietary lack. "Vitamin A deficiency is known to be associated with reduced iron binding capacity and transferrin saturation." (PMID 35719126, 2022).
whipworm infection (1 paper, 2019). "Upon whipworm infection, we also observed augmented levels of ferritin and transferrin, which are indicators of systemic infection, in IL-10 signalling-deficient, but not in WT mice." (PMID 30640950, 2019).
‐deficient (1 paper, 2019). "Abnormal findings in transferrin electrophoresis were contributory to the diagnosis of carbohydrate‐deficient glycoprotein syndrome type 1a." (PMID 31469254, 2019).
tumor (617 papers, 1976 to 2026). "We also showed that in vivo treatment causes permanent phenotypic changes to the tumor, which is driven by TF activation, but is overlooked when using genomic analyzes alone." (PMID 39514406, 2025). "Among iron-related markers, ceruloplasmin and the ceruloplasmin/transferrin ratio were significantly associated with tumor stage (pT), tumor size, metastasis, and tumor grade, particularly in males." (PMID 40507970, 2025). "H2AX, a critical component of the DNA damage response pathway, is associated with HCC radioresistance, while TF, a key regulator of iron metabolism, influences tumor growth and oxidative stress in HCC." (PMID 40307890, 2025). "Although ferritin, transferrin saturation, and hepcidin are commonly measured, their specificity for reflecting tumour-associated iron metabolism remains uncertain." (PMID 41153383, 2025). "We have previously shown that exogenous Factor V binds to tumour-associated TF, particularly when the TF is associated with phosphatidylserine-exposed tumour-membranes and vesicles." (PMID 39105809, 2024). "We connected the most consistent ligand-TF associations to putative upstream signaling by predicting inter-cellular ligand-receptor interactions at the tumor-stroma interface and their known signaling pathways." (PMID 38200223, 2024). "TF targeting therefore carries the potential to cause life-threatening on-target off-tumour affects, further emphasising the use of a dual recognition immunotherapy system." (PMID 39105809, 2024). "Dysregulation of gene expression due to loss of tumour suppression results in over-expression of TF in a number of cancers." (PMID 39105809, 2024). "I3C is reported to reduce the tumor multiplicity and the level of tumor-associated signature proteins, such as apolipoprotein A-1, a-antitrypsin precursor and transferrin." (PMID 36771198, 2023). "Jacalin is a suitable molecule for such targeting, as it specifically recognizes the tumor-associated Thomsen–Friedenreich (TF) antigen that is expressed on the glycosylated proteins in cancer cells." (PMID 38139227, 2023). "For example, PN-, MES- and CL-type tumours markedly differ in the expression of F3/TF (tissue factor) gene encoding the central cell-associated, transmembrane receptor and regulator of the extrinsic coagulation cascade." (PMID 38188342, 2023). "Beyond cancer-induced hypercoagulability, dysregulation of TF-associated signalling pathways and their constituents play an important role in tumour progression, particularly by impacting angiogenesis and tumour invasion." (PMID 37569483, 2023). "In 2012, scientists found that the small-molecule inducer erasin can kill RAS-mutant tumor cells, and can effectively upregulate transferrin (TF) content and reduce ferritin, thus causing intracellular iron overload." (PMID 35806144, 2022). "Similar antibody titers elicited for this construct in a MUC transgenic mouse model, and interestingly, these sera cross-reacted with the α-linked TF glycopeptides and recognized tumor cells with natural a-linked TF antigen." (PMID 35432351, 2022). "In terms of biological functions, a total of 1 834 TF genes, 2 570 essential genes, 575 house-keeping genes and 1 764 tumor-associated genes were respectively collected from public databases and the literature." (PMID 35821682, 2022). "Regarding tumor desmoplasia, we found also a statistical association between the expression of TF and this feature, as TF positive tumors showed a moderate/strong desmoplasia than TF negative tumors (p = 0.04)." (PMID 33572915, 2021). "EMT‐associated TF Snai1 and tumor invasive marker MMP‐9 showed elevated expression in the FSS‐HepG2 cells." (PMID 34260811, 2021). "In proliferating cancer cells, tumor hypoxia upregulates the expression of coagulation-promoting genes (e.g., TF and plasminogen activator inhibitor type 1) and causes a hypercoagulable state." (PMID 30959839, 2019).
tumor (continued). "An increased level of ferritin and decreased transferrin saturation were associated with higher tumour stage." (PMID 30640897, 2019). "Within pediatric tumors, C-dots conjugated to Dox and transferrin were able to cause tumor death at higher instances compared to free drug alone and shown to bypass the blood-brain barrier." (PMID 29439409, 2018). "For example, Reactome "lipid transport" lost cePathway relationship with PID "HIF1 TF" pathway with a strong over-representation in the ceRNA relationship loss in tumor (P-value = 0)." (PMID 29565967, 2018). "Recently, researchers demonstrated that in the tumor microenvironment, tumor-derived TF was the major cause of local thrombin generation." (PMID 28106852, 2017). "Ligand targeting of nanoparticles is a common targeting strategy, with tumor-associated dysregulated expression of the receptors of transferrin, folic acid, epidermal growth factor, and hyaluronic acid being particularly popular." (PMID 28325291, 2017). "The compounds immobilized on the glycochip include tumor‐associated glycans (SiaTn, Tn, TF, LeC, LeY, SiaLeA, and Manβ1‐4GlcNAcβ) and antibodies against human immunoglobulins IgG, IgA, and IgM." (PMID 26992329, 2016). "A marked positive granular signal for ALDH6A1 was evident in the cytoplasm of almost all tumor cells, probably associated with mitochondria, while a more diffuse cytosolic positivity was detected for Transferrin and Fascin-1 in ACC slices." (PMID 25691058, 2015). "Two novel tumour-associated carbohydrate antigen analogues with TN and TF determinants O-glycosidically linked to the side chain of Fmoc-β3hThr-OH have been prepared by Arndt–Eistert homologation of the corresponding glycosylated α-amino acids 1a and 1b." (PMID 20563275, 2010). "However, in tumor tissue, all these associations were lost, except for a preserved inverse correlation between vinculin and transferrin (ρ = −0.355, p = 0.040)." (PMID 40507970, 2025). "In this context, our finding of reduced % transferrin saturation and elevated ceruloplasmin/transferrin ratios in CRC patients may reflect a tumor-associated shift aimed at limiting ferroptotic vulnerability." (PMID 40507970, 2025). "Therefore, Lcn-2, a transferrin-independent iron carrier, which tumor-associated macrophages (M2-phenotype) increase its expression in the more aggressive tumor environment, allows cancer cells to acquire the additional necessary iron." (PMID 40450119, 2025). "Tumor-associated factors may regulate TF expression, resulting in differences between cancer types and subtypes, which is consistent with the findings observed in the present study." (PMID 38391918, 2024). "More studies have also proved that transferrin-coupled or covalently linked nanoparticles endow the NPs function of targeting tumors, which can more effectively realize the active targeting of drugs and achieve the purpose of tumor diagnosis or treatment." (PMID 37919282, 2023). "Indeed, within metastatic tumor cell lines, higher levels of GlcNAc, TF-antigen, NeuAc and Fuc motifs were associated with poor outcome, whereas higher levels of Man and Glc were linked with a longer PFS." (PMID 36891308, 2023). "We hypothesized that a dynamic TF regulatory program might underlie the progression from early to late dysfunction of tumor-infiltrating CD8+ T cells." (PMID 35668194, 2022). "Epithelial-to-mesenchymal transition, another hallmark of cancer, may also promote the release of TF-bearing EVs from tumor cells." (PMID 36013171, 2022). "Retrospective investigations on patient cohorts have also linked TF expression to survival outcomes in certain tumor types, suggesting that TF expression levels may help predict patient prognosis." (PMID 34452555, 2021).
tumor (continued). "Herein we report a distinct approach to S-linked glycosylations: a triflic acid catalyst is shown to enable the facile α-1,2-cis synthesis of thiol-oligosaccharides, glycopeptide of antimicrobial sublancin, S-linked tumor-associated TN/TF antigens, and thiol-glycolipids." (PMID 32110337, 2019). "Notably, the facile nature of this reaction have also successfully applied to the synthesis of S-linked glycopeptides of antimicrobial sublancin and tumor-associated mucin TN/TF antigens." (PMID 32110337, 2019). "In solid malignancies, TF expression has been linked to tumor angiogenesis." (PMID 26251762, 2015). "PNA lectin (specific to desialylated glycoepitops, namely to TF-antigen, is widely used in cancer research and diagnostic histopathology) showed preferential binding with differentiated melanoblast and melanocytes in tumor stroma." (PMID 24891277, 2014). "The induction of TF expression in tumour cells by thrombin indicates that tumour-associated PCA might have a positive-feedback effect on in vivo local propagation of thrombus by thrombin formation." (PMID 9820166, 1998). "Although contradictory reports point towards a transferrin-dependent as well as independent means of iron uptake by lymphocytes, it is intimately associated with the immune system and its enhanced levels are hallmarks of several neurodegenerative diseases and tumours." (PMID 34440444, 2021). "Concerning its role, the TF antigen has been implicated in cell adhesion, as it favors the attachment of tumor cells to the endothelium through the expression of galectin-3 by endothelial cells, supporting its role in tumor invasion and therefore contributing to metastasis." (PMID 33572915, 2021). "Tumor cells exploit the transferrin-transferrin receptor (TFRC) axis to competitively limit macrophage iron uptake, lowering intracellular ferrous iron." (PMID 41355954, 2026). "When TF groupings were incorporated, four of the five NE pathways ranked among the top 25 most informative, indicating their significance in differentiating tumor grades." (PMID 40770488, 2025). "For instance, coupling doxorubicin to transferrin has been shown to enhance tumor specificity and reduce off-target toxicities, such as cardiotoxicity, in breast cancer and leukemia models." (PMID 41301848, 2025). "Further modification with targeting ligands, such as mannose (MAN) or transferrin (Tf), enables targeted recognition of specific receptors on tumor cells or the BBB (Eroğlu and İbrahim, 2020)." (PMID 41368585, 2025). "Through the specific binding between TfR and transferrin (Tf), the system enables targeted delivery of anti-tumor agents to glioma cells, achieving dual functions of MRI-based glioma imaging and targeted therapy." (PMID 40723232, 2025). "Some studies have demonstrated that transferrin-conjugated nanoparticles can effectively deliver chemotherapeutic agents directly to tumor cells, thereby minimizing systemic toxicity and enhancing therapeutic outcomes." (PMID 40303995, 2025). "Targeted CDs functionalized with ligands such as folic acid, transferrin, or specific peptides can selectively accumulate in tumor tissues overexpressing the corresponding receptors." (PMID 41470537, 2025). "The findings demonstrated that T7-exos achieved a significant level of brain targeting, successfully traversing the blood-brain barrier, binding to transferrin on tumor cells, and substantially reducing tumor size." (PMID 40141135, 2025). "Examples of targeted ligands from drug delivery systems used in active targeting to tumor cells include folate, transferrin, and galactosamine." (PMID 39861768, 2025). "Transferrin overexpression significantly enhanced tumor metastasis, while knockdown of transferrin inhibited it." (PMID 39810853, 2025).